PRKAB1 (protein kinase AMP-activated non-catalytic subunit beta 1)
Description:
Non-catalytic subunit of AMP-activated protein kinase (AMPK), an energy sensor protein kinase that plays a key role in regulating cellular energy metabolism. In response to reduction of intracellular ATP levels, AMPK activates energy-producing pathways and inhibits energy-consuming processes: inhibits protein, carbohydrate and lipid biosynthesis, as well as cell growth and proliferation. AMPK acts via direct phosphorylation of metabolic enzymes, and by longer-term effects via phosphorylation of transcription regulators. Also acts as a regulator of cellular polarity by remodeling the actin cytoskeleton; probably by indirectly activating myosin. Beta non-catalytic subunit acts as a scaffold on which the AMPK complex assembles, via its C-terminus that bridges alpha (PRKAA1 or PRKAA2) and gamma subunits (PRKAG1, PRKAG2 or PRKAG3).
Synonyms: AMPK; HAMPKb
Tractability: Small molecule: a drug acting on it is in phase 2 or 3 trials; a structure with a bound ligand is known; a high-quality ligand is known; it belongs to a druggable protein family. PROTAC: ubiquitination databases record sites on it; its protein half-life has been measured; a small molecule that binds it is known.
Target class: Kinase; Protein kinase regulatory subunit; Enzyme
Safety:
Unwanted effects reported when the protein is acted on. In parentheses: how it was acted on, where the effect was seen, and who reports it.
heart disease (cardiovascular system; source: Force et al. (2011))
Gene: Protein-coding gene on chromosome 12 (119,667,864 to 119,681,624, forward strand). Ensembl gene ENSG00000111725.
Subcellular location (Human Protein Atlas): Cytosol; Nucleoplasm; Primary cilium transition zone
Pathways (Reactome):
Autophagy: Lipophagy; Macroautophagy
Immune System: AMPK-induced ERAD and lysosome mediated degradation of PD-L1(CD274)
Neuronal System: Activation of AMPK downstream of NMDARs
Organelle biogenesis and maintenance: Activation of PPARGC1A (PGC-1alpha) by phosphorylation
Signal Transduction: Energy dependent regulation of mTOR by LKB1-AMPK
Vesicle-mediated transport: Translocation of SLC2A4 (GLUT4) to the plasma membrane
Gene Ontology:
Molecular function: protein binding; protein kinase binding
Biological process: cellular response to nutrient levels; positive regulation of cold-induced thermogenesis; signal transduction
Cellular component: nucleotide-activated protein kinase complex; nucleus; cytoplasm; cytosol; endoplasmic reticulum lumen; nucleoplasm; protein-containing complex
Genetic constraint (gnomAD): Loss-of-function variants: 16 observed, 32.08 expected, observed/expected ratio (o/e) 0.5, 90% interval 0.34 to 0.76. The upper end of that interval is the gene's LOEUF score, 0.76, which puts it in group 3 of 6, group 1 being the genes least tolerant of losing a copy. Missense variants: 260 observed, 366.04 expected, observed/expected ratio (o/e) 0.71, 90% interval 0.64 to 0.79. Synonymous variants: 140 observed, 147.82 expected, observed/expected ratio (o/e) 0.95, 90% interval 0.82 to 1.09.
Homologues: Orthologues: chimpanzee PRKAB1 (100% identical), macaque PRKAB1 (100% identical), dog PRKAB1 (99% identical), guinea pig Prkab1 (99% identical), rabbit PRKAB1 (98% identical), mouse Prkab1 (97% identical), rat Prkab1 (96% identical), tropical clawed frog prkab1 (83% identical), pig PRKAB1 (81% identical), zebrafish prkab1a (80% identical), zebrafish prkab1b (74% identical), Drosophila melanogaster alc (53% identical), and 3 more. Paralogues in human: PRKAB2 (70% identical).
Diseases named in the same sentence as PRKAB1 in open-access papers:
PRKAB1 is named in the same sentence as 38 diseases in open-access papers, as found by Europe PMC text mining. Sharing a sentence is not in itself a finding about the gene and the disease. The quoted sentences say what the papers report.
type 2 diabetes (3 papers, 2015 to 2026). "Metformin, the first line treatment for type 2 diabetes, targets the circadian gene PRKAB1, which encodes for a regulatory subunit of the AMP-activated protein kinase (AMPK), a master regulator of energy metabolism." (PMID 41303713, 2025). "Upregulated canonical pathways included those related to adipocytokine, insulin, and type 2 diabetes signaling (e.g., Adipor1, Prkab1, and Acacb)." (PMID 25744495, 2015).
hepatocellular carcinoma (2 papers, 2021 to 2024). A malignant tumor that arises from hepatocytes. "When the expression level and activity of PRKAB1 decrease, it can inhibit the process of autophagy induction of hepatocellular carcinoma." (PMID 33777735, 2021).
lymphoma (2 papers, 2020 to 2023). A malignant (clonal) proliferation of B- lymphocytes or T- lymphocytes which involves the lymph nodes, bone marrow and/or extranodal sites.
Obesity (2 papers, 2011 to 2021). Accumulation of substantial excess body fat. "Taken together, these results suggest that Sjp40, through its interaction with the miR-802/Prkab1 axis, has potential to become a novel treatment for obesity-related fatty liver disease." (PMID 33391522, 2021). "In the 12q24 area there are other genes that might be involved in the phenotype including THRAP2, TBX5 and PTPN11 for cardiac and great vessel anomalies; TBX5, CMKLR1, and TRPV4 for skeletal defects; PRKAB1, GPR109A, and GPR109B for increased hunger and obesity." (PMID 21457577, 2011).
prostate carcinoma (2 papers, 2018 to 2020). A carcinoma that arises from epithelial cells of the prostate gland. "In prostate cancer, high-level amplification of PRKAB1, PRKAB2, PRKAG2, and PRKAG3 occurs in up to 6.3%, 6.8%, 4.1%, and 2% of cases respectively." (PMID 32630372, 2020). "Metformin and Phenformin (targeting on PRKAA1/PRKAB1 were used for eliminate prostate cancer stem cells." (PMID 29723215, 2018). "In a Pten-deleted prostate cancer mouse model, Camkk2 deletion or CAMKKβ pharmacological inhibition has been shown to suppress prostate tumorigenesis and reduce de novo lipogenesis, whereas Prkab1 (AMPK-β1) and Pten co-deletion accelerates tumor progression." (PMID 32630372, 2020).
anal carcinoma (1 paper, 2024). "In SMR analyses, ABCC8/KCNJ11, DPP4, PPARG, ETFDH, and PRKAB1 were associated with anal carcinoma, cardia cancer, and pancreatic cancer." (PMID 38504335, 2024). "Associations of ABCC8/KCNJ11, DPP4, GLP1R, GPD2, PPARG, PRKAB1, and SLC5A2 with anal carcinoma, cardia cancer, gastric cancer, HCC, ICC, pancreatic cancer, and rectum cancer were revealed in two-sample MR analyses." (PMID 38504335, 2024). "Weak evidence indicated the connections of GLP1R, GPD2, and PRKAB1 with anal carcinoma, cardia cancer, ICC, and rectum cancer." (PMID 38504335, 2024). "Furthermore, ABCC8/KCNJ11, DPP4, GLP1R, PRKAB1, and GPD2 shared causal variants within anal cancer, HCC, ICC, pancreatic cancer, and rectum cancer according to the colocalization analyses." (PMID 38504335, 2024).
breast carcinoma (1 paper, 2022). "For example, the mRNA signatures ETFDH, EGF, PRKAB1, ALOX5, DHRS9, MTHFR, and MGHH are in the maximum interaction network and are connected to other breast-cancer-related, frequently altered genes." (PMID 36551179, 2022).
ciliopathy (1 paper, 2022). A genetic disorder of the cellular cilia or the cilia anchoring structures, the basal bodies, or of ciliary function. "Histological and morphological evidence of phenotypes found in ciliopathies in knockout mouse lines are presented as examples (genes Abi2, Wdr62, Ap4e1, Dync1li1, and Prkab1)." (PMID 36456625, 2022). "Five of these genes predicted to have ciliary interaction (Abi2, Wdr62, Ap4e1, Dync1li1, and Prkab1) had abnormal morphological features detected by imaging that are consistent with the spectrum of phenotypes observed in ciliopathies." (PMID 36456625, 2022). "Abi2, Ap4e1, and Prkab1 therefore have strong evidence to be novel candidate ciliopathy genes." (PMID 36456625, 2022).
diabetes (1 paper, 2014). "Furthermore, two diabetes related drugs, Phenformin and Metformin, target the two subunits of AMPK, PRKAA1 and PRKAB1." (PMID 25399255, 2014).
endometriosis (1 paper, 2025). The growth of functional endometrial tissue in anatomic sites outside the uterine body. "In the GSE141549 validation cohort, only DDR2, ESM1, and PRKAB1 maintained the same expression trends as observed in the merged dataset, with statistically significant differences between normal and endometriosis samples (DDR2, p < 0.001; ESM1, p = 0.002; PRKAB1, p < 0.001)." (PMID 41424583, 2025). "In the merged dataset, the expression levels of these six genes—DDR2, ENO3, ESM1, NMBR, PRKAB1, and PRPF19—showed significant differences between normal and endometriosis samples (DDR2, p < 0.001; ENO3, p < 0.001; ESM1, p < 0.001; NMBR, p = 0.002; PRKAB1, p < 0.001; PRPF19, p < 0.001)." (PMID 41424583, 2025).
epilepsy (1 paper, 2022). A brain disorder characterized by episodes of abnormally increased neuronal discharge resulting in transient episodes of sensory or motor neurological dysfunction, or psychic dysfunction. "The nomogram, using RELA, PRKAB1, TNFRSF1A, CAMKK2, and CPT1B, was next confirmed as a reliable predictive model for epilepsy that would bring patients a net clinical benefit when the threshold probability ranged from 0.1 to 1.0." (PMID 36138892, 2022). "Upregulation of PRKAB1 and CAMKK2 in this study underscored the pivotal role of energy homeostasis in epilepsy." (PMID 36138892, 2022).
Fanconi Anaemia (1 paper, 2022). "In addition, the top two enriched KEGG pathways were: 1) the Fanconi Anaemia pathway (represented by ATR, BRIP1, ERCC4, FANCC and POLH) and the FoxO signalling pathway (represented by CREBBP, NLK, PRKAA2, PRKAB1, PTEN and STK11)." (PMID 35768547, 2022).
pancreatic cancer (1 paper, 2024). "Moreover, ABCC8 (OR = 1.142; 95% CI: 1.013–1.287; P-value = 0.030), ETFDH (OR = 1.249; 95% CI: 1.006–1.550; P-value = 0.044), and PRKAB1 (OR = 0.798; 95% CI: 0.662–0.962; P-value = 0.018) were associated with pancreatic cancer risks." (PMID 38504335, 2024).
prostate adenocarcinoma (1 paper, 2023). "For example, one study reported that PRKAB1 is overexpressed in metastatic vs. primary PC, indicating an oncogenic function, whereas another study showed that deletion of the PRKAB1 gene in mouse models conferred earlier prostate adenocarcinoma development, indicating a tumor suppressor function." (PMID 37270558, 2023).
rectum cancer (1 paper, 2024). "Therefore, in our study, we conducted a detailed investigation into the three drug targets of metformin (ETFDH, GPD2, and PRKAB1), and the discovery cohorts and integrated results revealed that GPD2 has an inhibitory effect on the occurrence of rectum cancer." (PMID 38504335, 2024).
renal cell carcinoma (1 paper, 2011). "Finally, we present a case study of the use of caCORRECT to reliably identify biomarkers for renal cell carcinoma, yielding two diagnostic biomarkers with potential clinical utility, PRKAB1 and NNMT." (PMID 21957981, 2011).
renal oncocytoma (1 paper, 2017). "We have identified missense mutations in DCLRE1C and frame shift mutations in PRKAB1 from renal oncocytoma patient samples." (PMID 29285300, 2017).
Salmonella Infections (1 paper, 2018). Infections with bacteria of the genus SALMONELLA. "On the other hand, FOXO signaling (TNFSF10, PRKAB1, GADD45B, STK4, STAT3), Salmonella infection (ARPC2, ARPC5L, CCL3L3, CCL4) and lysosome (LAPTM4B, HGSNAT, CD164, ATP6V0A2) pathways were up-regulated, albeit weakly, in the HLA-DR- Teff subset." (PMID 30231065, 2018).
schizophrenia (1 paper, 2024). A major psychotic disorder characterized by abnormalities in the perception or expression of reality. "Expression of the ‘Macroautophagy’ genes AMBRA1, PRKAB1, TUBA1A, TUBB2A, and TUBA4A was restored in the AT-schizophrenia group." (PMID 38648100, 2024).
steatosis (1 paper, 2014). Increased lipid within the cytoplasm of cells. "Intriguingly, the findings that Ampkβ1−/− mice are protected from HF diet-induced steatosis and that Ampkβ1 (i.e., Prkab1) is upregulated in Nrf2−/− mice suggest that it may contribute to exacerbation of steatosis in Nrf2−/− liver." (PMID 24958099, 2014).
T-cell lymphomas (1 paper, 2019).
tumor (12 papers, 2016 to 2025). "It is known that mitogen-activated protein kinases (MAP4K1 and MAP4K4) and the insulin resistance pathway (PRKCD and PRKAB1) may be associated with tumor progression through modulation of gene expression responsible for cell cycle, proliferation, and growth." (PMID 35453789, 2022). "Our results are predominantly in line with a tumor suppressor function in C4 mCRPC cells, as we showed that PRKAB1 knockout increased cabazitaxel resistance." (PMID 37270558, 2023). "We previously reported that deletion of Prkab1, encoding the β1 subunit of AMPK, increased cancer progression in Pten−/− mice, suggesting that AMPK activation could have a tumor-suppressive effect on PCa in vivo." (PMID 37061917, 2023). "PRKAB1 has not previously been associated with taxane resistance, and it is currently unclear whether PRKAB1 has an oncogenic or tumor suppressor effect in PC, as previous studies have shown contrasting results." (PMID 37270558, 2023). "We identify PRKAB1 as a key upstream node and show that PF-06409577, a clinically safe first-in-class agonist, triggers CDX2-restoration, cell-type specific differentiation, and anti-tumor responses." (PMID 41118768, 2025). "Following the co-expression and network analyses, this signature was found to be enriched for genes involved in the regulation of the stroma component of the tumor (TDO2, STEAP1) as well as Treg cells (SLC16A1, PRKAB1) and myeloid cell (APOBEC3A, MERTK, SNX29) subsets." (PMID 36216827, 2022). "Another mouse model used prostate -specific knockouts of both the tumour-suppressor gene Pten and Prkab1; although the additional knockout of AMPK-β1 did not affect prostate size, it did result in a higher proliferative index and pathological grade of tumour." (PMID 33375416, 2020). "Additionally, for the genes PRKAB1, PRKAB2, PER1, PER2, and PER3, methylation was observed in all samples, regardless of the tumor grade." (PMID 39001398, 2024). "However, in both this model and the previous one, the knockouts of AMPK genes (Prkaa1 or Prkab1) were global rather than T-cell specific, so it was not possible to conclude that these were cell-intrinsic effects on AMPK in the tumour progenitor cells themselves." (PMID 33375416, 2020).
cancer (7 papers, 2008 to 2026). A tumor composed of atypical neoplastic, often pleomorphic cells that invade other tissues. "As indicated by studies conducted on various types of cancer, lower expression of PRKAB1 and PRKAB2 resulted in increased cell proliferation and enhanced metastatic potential of tumors." (PMID 39001398, 2024). "Importantly, PF failed to reinstate CDX2, alter differentiation or stemness markers, or induce cell death in PRKAB1-depleted cells, confirming target specificity of its anti-cancer effects." (PMID 41118768, 2025). "Similar to the α isoforms, an intriguing difference between β1 and β2 concerns the nature of genetic changes in the respective genes (PRKAB1 and PRKAB2) in the cancer genome databases." (PMID 26934201, 2016).
infection (1 paper, 2021). The state of being infected such as from the introduction of a foreign agent such as serum, vaccine, antigenic substance or organism. "Using qRT-PCR, we demonstrated that S. japonicum infection significantly increased expression of Prkab1, but not Ppp2ca, and Pafah1b1 in the livers of ND-fed mice compared with that in the control mice with infection." (PMID 33391522, 2021).
PRKAB1 also shares sentences with these, for which no sentence is quoted: age (1 paper); anemia (1); arrhythmogenic right ventricular cardiomyopathy (1); astrocytic tumor (1); cardia cancer (1); colorectal adenocarcinoma (1); dilated cardiomyopathy (1); fatty liver disease (1); gastric cancer (1); hematoma (1); hypertrophic cardiomyopathy (1); intrahepatic cholangiocarcinoma (1); oncocytoma (1); Splenomegaly (1).